PSMA4 (proteasome 20S subunit alpha 4)
Diseases named in the same sentence as PSMA4 in open-access papers (continued):
Sharing a sentence is not in itself a finding about the gene and the disease.
asthma (1 paper, 2026). "Five druggable genes significantly associated with asthma were identified in whole blood (IRF1, OXER1, PSMA4, UNC13D, and HLA‐DRB1) and one in lung tissue (CD226)." (PMID 41573111, 2026). "IRF1 (PPH4/PPH3 + PPH4 = 0.975), OXER1(PPH4/PPH3 + PPH4 = 0.967), PSMA4(PPH4/PPH3 + PPH4 = 0.972), UNC13D (PPH4/PPH3 + PPH4 = 0.989) and HLA‐DRB1(PPH4/PPH3 + PPH4 = 0.948) expression had significant colocalization associations with asthma." (PMID 41573111, 2026).
atherosclerosis (1 paper, 2023). A disease characterized by the build-up of fatty material and calcium deposition in the arterial wall resulting in partial or complete occlusion of the arterial lumen. "Hence, it could be suggested that the rs1051730A allele, correlated with increased expression of PSMA4, may be linked to atherosclerosis through UPR activation." (PMID 36836853, 2023).
cutaneous melanoma (1 paper, 2017). A primary melanoma arising from atypical melanocytes in the skin. "In Talantov's dataset, PSMA4 was higher in 45 cutaneous melanomas than in seven normal skin samples." (PMID 27966459, 2017).
heart failure (1 paper, 2022). Inability of the heart to pump blood at an adequate rate to meet tissue metabolic requirements. "Proteasome 26S subunit, ATPase 2 (PSMC2) and proteasome 20S subunit Alpha 4 (PSMA4) identified by a CRISPR study were associated with many genetic risks of diseases, ranging from heart failure to MDD." (PMID 35903362, 2022).
invasive breast carcinoma (1 paper, 2017). A carcinoma that infiltrates the breast parenchyma. "PSMA4 was upregulated in invasive ductal breast carcinoma and lobular breast carcinoma in datasets from Zhao and Radvanyi, while it was downregulated in invasive breast cancer compared with normal breast tissues in Finak's dataset." (PMID 27966459, 2017).
lung squamous cell carcinoma (1 paper, 2024). "For lung squamous cell carcinoma, 11 genes were causally related, comprising COPA, NCSTN, U91328.19, GABBR1, IER3, HLA-DQB1-AS1, HLA-DQB2, ANKRD26, PKD2L1, PSMA4 and RAD51C." (PMID 38834983, 2024).
lymphopenia (1 paper, 2022). Reduction in the number of lymphocytes. "Patients with high PSMA4 and PSMA5 mRNA expression suggested more acute lymphopenia, more severe hypoxemia and higher concentrations of C-reactive protein and ferritin in plasma." (PMID 35327634, 2022).
mild cognitive impairment (1 paper, 2022). "PSMA4 is also a gene bridging between mild cognitive impairment (MCI) and AD." (PMID 35883662, 2022).
nicotine-addiction (1 paper, 2021). "Several well-known nicotine-addiction-associated genes, including CHRNA5, PSMA4, and CHRNA3, were identified and their cross-brain-tissue-association patterns were revealed." (PMID 35052378, 2021).
nonalcoholic steatohepatitis (1 paper, 2025). "Indeed, the PSMA4 gene has been reported to impact a series of inflammatory disorders, including nonalcoholic steatohepatitis and ankylosing spondylitis arthritis." (PMID 40116326, 2025).
osteoporosis (1 paper, 2025). A condition of reduced bone mass, with decreased cortical thickness and a decrease in the number and size of the trabeculae of cancellous bone (but normal chemical composition), resulting in increased fracture incidence. "In support of this hypothesis, our MR analysis revealed a significant association between increased PSMA4 expression and a higher risk of osteoporosis." (PMID 40764749, 2025). "The analysis revealed that FMO4 and PSMA4 were consistently downregulated in osteoporosis patients, whereas VEGFA exhibited significantly increased expression levels." (PMID 40764749, 2025). "This study identified key genes linked to osteoporosis, such as FMO4, PSMA4 and VEGFA, and explored their potential molecular mechanisms and regulatory networks." (PMID 40764749, 2025). "This study identifies FMO4, PSMA4 and VEGFA as key genes associated with osteoporosis, analyses their molecular mechanisms and regulatory networks and elucidates their relationship with the disease." (PMID 40764749, 2025). "FMO4 and NOV were associated with a decreased risk of osteoporosis, whereas MAP2K5, PSMA4, SCARB1 and VEGFA were linked to an increased risk." (PMID 40764749, 2025). "Three genes—FMO4, PSMA4 and VEGFA—were significantly associated with osteoporosis risk." (PMID 40764749, 2025). "In this study, we systematically identified VEGFA, PSMA4 and FMO4 as genes significantly associated with osteoporosis risk using MR, and explored their expression patterns using single‐cell RNA sequencing (scRNA‐seq) data from osteoporosis patients." (PMID 40764749, 2025). "These immune populations are known to modulate inflammation, bone resorption and remodelling, reinforcing the immunomodulatory relevance of FMO4, PSMA4 and VEGFA in osteoporosis pathophysiology." (PMID 40764749, 2025). "Pathway enrichment analyses indicated that FMO4, PSMA4 and VEGFA may influence osteoporosis progression through several critical signalling pathways, including calcium signalling, Wnt/β‐catenin, PI3K/Akt and Hedgehog signalling." (PMID 40764749, 2025).
pancreatic cancer (1 paper, 2024). "Moreover, FKBP1A and PSMA4 mRNA expression levels tended to be higher in advanced pancreatic cancer stages." (PMID 38570626, 2024). "Our results revealed high mRNA expression levels in WBCs of pancreatic cancer patients in all selected genes, including FKBP1A (p < 0.0001), PLD1 (p < 0.0001), and PSMA4 (p = 0.0002)." (PMID 38570626, 2024). "The quantification showed that mRNA levels of all candidate genes were significantly higher in pancreatic cancer samples compared to controls (p < 0.0001 in FKBP1A, p < 0.0001 in PLD1, and p = 0.0002 in PSMA4)." (PMID 38570626, 2024).
rectal adenoma (1 paper, 2017). "Moreover, PSMA3 and PSMA4 were also upregulated in rectal adenoma compared with normal tissues from Sabates-Bellver's datasets." (PMID 27966459, 2017).
small cell lung carcinoma (1 paper, 2024). Small cell lung cancer (SCLC) is a highly aggressive malignant neoplasm, accounting for 10-15% of lung cancer cases, characterized byrapid growth, and early metastasis. "Only one gene was found to have a causal relationship with small cell lung cancer, namely PSMA4." (PMID 38834983, 2024).
cancer (13 papers, 2017 to 2025). A tumor composed of atypical neoplastic, often pleomorphic cells that invade other tissues. "By regulating key cell cycle proteins, PSMA4 ensures that cancer cells bypass normal checkpoints, thereby promoting uncontrolled proliferation." (PMID 39529882, 2024). "Our findings are in concordance with the existing literature that implicates PSMA4 in cancer biology." (PMID 39529882, 2024). "And PSMA4 plays a role in promoting cancer cell proliferation, including proliferation and apoptosis." (PMID 37035734, 2023). "PSMA4, another proteasome, shares a similar fate as PSMA1, being that it is downregulated in cancer cells when those cells are treated with an anti-cancer compound." (PMID 38732562, 2024). "In our comparison between the normal and early-stage cancer groups, FKBP1A showed the highest significant p-value (p < 0.0001) among all candidate genes (PLD1, p = 0.0078, PSMA4, p = 0.0165)." (PMID 38570626, 2024). "For instance, seven PSM genes (i.e. PSMA1, PSMA4, PSMC1, PSMC3IP, PSMD13, PSMG2-3 (PSM class I/II/V)) were overexpressed in the majority of the 16 cancer types." (PMID 36123629, 2022). "Some genes comprising CRRS have been reported to involve the malignant phenotypes in different cancers, such as CRTC2, FBXL22, OPRL1, and PSMA4." (PMID 34862329, 2021). "For what concerns the in vivo tumor expression of proteasome subunits and ubiquitin, it is first worth underscoring that the immunostaining of two constitutive structural subunits, such as PSMA4 and PSMD4, was very faint in cancer cells of DMSO-treated animals." (PMID 34561494, 2021).
tumor (7 papers, 2010 to 2024). "Next, we assessed whether the expression of selected genes (FKBP1A, PLD1, and PSMA4) was correlated to the tumor stage." (PMID 38570626, 2024). "This could involve the development of small molecule inhibitors, monoclonal antibodies, or other modalities designed to interfere with the proteolytic function of PSMA4, potentially slowing tumor progression or enhancing the efficacy of existing treatments." (PMID 39529882, 2024). "In addition, tumor vessels density and expression of some proteasome structural subunits (PSMA4, PSMD4, PSME1) and ubiquitin were evaluated." (PMID 34561494, 2021). "In addition, by participating in the degradation of immunomodulatory proteins, PSMA4 may influence the tumor immune microenvironment by regulating the expression of tumor antigens and evading immune surveillance mechanisms." (PMID 39529882, 2024). "Excess dietary iron in tumor tissues was also associated with significant changes (generally, increases; p ≤ 0.05) in proteins involved in modulating cell protein integrity (HSPA5, HSPA9, ITGB1, PSMA4, DPP7, and PEPD), cell mobility and growth (CAPZB), and immunologic factors (FCGBP)." (PMID 38732562, 2024).
infection (2 papers, 2019 to 2022). The state of being infected such as from the introduction of a foreign agent such as serum, vaccine, antigenic substance or organism. "Our study found a set of proteasome-encoding genes that included PSMA1, PSMD10, PSMD14 and PSMA4, that were all down-regulated during the early phase of infection." (PMID 30789917, 2019).
diseases of the central nervous system (1 paper, 2025). "These include genes involved in neurodegeneration (EIF5), diseases of the central nervous system (IPO13, ST3GAL3), tobacco addiction (CHRNB4, PSMA4), fatty acid metabolism (ACSBG1), and skin conditions (HYI, ELOVL1)." (PMID 40074595, 2025).
PSMA4 also shares sentences with these, for which no sentence is quoted: aortic aneurysm (2 papers); glomerulonephritis (2); adenocarcinoma (1); autism (1); coronary artery disease (1); depression (1); diabetes (1); emphysema (1); gastric cancer (1); hidradenitis suppurativa (1); invasive ductal breast carcinoma (1); leukemia (1); lobular breast carcinoma (1); lymphoma (1); malaria (1); nephritis (1); non-small cell lung carcinoma (1); Peri-Implantitis (1); pneumonia (1); psychiatric disease (1); Rapid-onset dystonia-parkinsonism (1); varicocele (1).